RNY1P3 (RNY1 pseudogene 3)
Gene: Miscellaneous RNA gene on chromosome 13 (25,950,704 to 25,950,821, reverse strand). Ensembl gene ENSG00000223158.
Homologues: Orthologues: chimpanzee Y_RNA (100% identical). Paralogues in human: Y_RNA (77% identical), RNY1 (76% identical), Y_RNA (76% identical), RNY1P11 (75% identical), Y_RNA (75% identical), RNY1P7 (75% identical), Y_RNA (74% identical), RNY1P8 (73% identical), Y_RNA (73% identical), Y_RNA (72% identical), RNY1P13 (71% identical), Y_RNA (71% identical), and 90 more.